FOXJ1 (forkhead box J1)
Diseases named in the same sentence as FOXJ1 in open-access papers (continued):
Sharing a sentence is not in itself a finding about the gene and the disease.
infection (23 papers, 2013 to 2025). The state of being infected such as from the introduction of a foreign agent such as serum, vaccine, antigenic substance or organism. "To investigate whether infection results in loss of ciliated cell identity, we stained for the key transcription factor FOXJ1 that is required for the formation of motile cilia, and indeed MERS-CoV+ cells were FOXJ1dim." (PMID 40048293, 2025). "In humans, it has been demonstrated in vitro and in vivo that infection is associated with decreased expression of the transcription factor Forkhead box protein J1 (FOXJ1) in the respiratory epithelia, which is required for the correct docking of basal bodies as well as cilia motility and length." (PMID 35563514, 2022). "However, the observation of a concurrent FOXJ1 loss argues against a purely mechanical dislocation of cilia by virions and suggests that the cilia retraction could be the consequence of FOXJ1 loss, which is triggered by infection." (PMID 35563514, 2022). "Plscr1floxStop and Plscr1floxStop;Foxj1-Cre+mice were exposed to sublethal (300 pfu) influenza A virus (IAV) (WSN) infection and sacrificed at 3 dpi." (PMID 41439508, 2025). "At 5 days post infection, 86% of the McIdas-infected cells expressed FoxJ1 and showed accumulation of multiple basal bodies, based on Pericentrin immunostaining (Fig. EV4B,C)." (PMID 39468302, 2024). "Our analysis showed that 14 days post infection 49% of McIdas- and 19% of GemC1-infected astrocytes were expressing FoxJ1 (F and EV2D)." (PMID 39468302, 2024). "Downregulation of Foxj1, a regulator of ciliogenesis, has been suggested as the upstream mechanism of cilia loss in SARS-CoV-2–infected HTBE cells immediately after infection." (PMID 36625345, 2023). "Infection also results in a progressive decline in cells expressing the regulator of ciliogenesis FOXJ1, which persists beyond virus clearance and the termination of inflammatory changes." (PMID 35563514, 2022). "Extended culture of HRV-infected epithelium was accompanied by almost complete normalization of mRNAs deregulated during the acute infection phase, including FOXJ1 and DNAI1, which suggests a quick restoring of ciliogenesis." (PMID 34140575, 2021). "Taken together our findings are consistent with an initial phase of multiciliated cell dedifferentiation triggered by the early downregulation of Foxj1, compounded by multiciliated cell death at a more advanced stage of infection." (PMID 34272374, 2021). "Therefore, we monitored the infection efficiency of SARS-CoV-2 in FOXJ1+ ciliated cells and found significantly less SARS-N+; FOXJ1+ ciliated cells in NDUFA4−/− iPSC-derived airway organoids than in WT iPSC-derived airway organoids." (PMID 36206731, 2022). "The late decrease in transcripts encoding ciliogenesis regulators (FOXJ1, RFX3) and ciliary components (DNAH7) may in part result from the death of ciliated cells detectable at a more advanced stage of infection." (PMID 34272374, 2021). "Consistent with our gene expression analysis, HRV-A16 infection resulted in an increase in marker of goblet cells (Mucin 5AC-positive cells) and a decrease in markers of ciliated cells (acetylated α-tubulin [structural protein] and FOXJ1 [transcription factor involved in ciliogenesis])." (PMID 32637364, 2020). "Following infection of the bronchial epithelium with SARS-CoV-2, a reduction in the expression of cilia regulatory factors, including FOXJ1, RFX3, and DNAH7, was observed." (PMID 39195243, 2024). "To better understand the dynamics of FoxJ1, acetylated alpha-tubulin, and CDHR3 during infection, we analyzed global protein expression by Western blot (WB) and quantified fluorescence levels following immunostaining specifically in infected cells." (PMID 34995322, 2022). "This increase was accompanied by a dose-dependent decrease in FOXJ1 expression at both 48 and 72 h, and a decrease of SCGB1A1 at MOI 5 and 72 h after infection." (PMID 32637364, 2020).
infection (continued). "To support our flow cytometry analysis, we collected mice 14 days post-infection with Mal/04-Cre and cross-sectioned tracheas to stain for the epithelial markers SSEA-1, KRT5 and FOXJ1 using microscopy." (PMID 30770807, 2019). "Beyond the intrinsic variation expected across cultures in this model system, neither FoxJ1 nor acetylated alpha-tubulin protein levels were dramatically altered over the course of infection." (PMID 34995322, 2022).
cancer (17 papers, 2010 to 2025). A tumor composed of atypical neoplastic, often pleomorphic cells that invade other tissues. "The biological significance and prognostic association of FOXJ1 in cancer is varied." (PMID 36323878, 2023). "The observed up-regulation in all three cancer nodules of FOXJ1 (13.75× in “A”, 18.51 in “B” and 20.39 in “C”) and PLA2G2A (6.68× in “A”, 18.75× in “B” and 23.61× in “C”) confirmed findings of other authors." (PMID 34209090, 2021). "This suggests that NANOG high/FOXJ1 low are more akin to cancer stem cells, which may be more likely chemo-resistant and thereby less susceptible to chemotherapy, leading to poor prognosis." (PMID 36323878, 2023). "Notably, LIHC, KIRC, and OV cancers had the 40 same upregulated genes, such as FOXJ1, LOC100128674, MAGEC1, and PAGE2." (PMID 35813444, 2022). "The downregulated genes that we have identified in NPC, such as MSMB, UPK1B, and FOXJ1, may be associated with the development or progression of NPC and may play different roles from their roles in other cancers." (PMID 33564686, 2021). "It is unclear how FOXJ1 could control the abundance of mutant APC, and it should be noted that FOXJ1 is more commonly associated with cancers in which APC mutations are infrequent." (PMID 34298659, 2021). "An important feature of our model is that overexpression of Sox2 leads not only to distal hyperplasia and cancer but also to development of a pseudostratified epithelium with p63-positive cells adjacent to the basal lamina and FoxJ1 cilliated cells reaching to the apical surface." (PMID 20548776, 2010). "However, the precise mode by which FOXQ1 and FOXJ1 activate Wnt signaling, and whether this function is relevant for their role in cancer biology, requires further investigation." (PMID 34298659, 2021). "Regarding the analysis of MCC differentiation in BC, the main limitations were the study of only FOXJ1 as a marker of multiciliation, the use of TMA sections, and the analysis of only luminal carcinomas." (PMID 39936988, 2025). "mRNA data from an independent cohort showed higher FOXJ1 and CAPS expression in serous borderline tumors and low-grade carcinomas compared to HGSOC." (PMID 36552773, 2022). "Meanwhile, FOXJ1, negatively regulated by NANOG, exerts anti-cancer proliferation, migration, and invasion activity in OC43." (PMID 33785763, 2021). "Others have demonstrated the regulation of FOXC1/2, FOXD3, FOXJ1, and FOXN1 expression by β-catenin/TCF in different contexts, but the relevance for cancer biology is less clear in these cases." (PMID 34298659, 2021). "This analysis validated the identification of genes that could be specific to cancer biology, such as IL7R, JUN, NR3C1 in Ba/Sq subtype, NPAS2, FOXQ1, GRHL3 in Luminal samples, or CDKN2C, FOXJ1, MEIS2, FGFR3 in both subtypes." (PMID 36944729, 2023). "FOXJ1 and FOXD3 were the members of forkhead box (FOX) and genes in FOX family played key roles in many cancer-related biological processes, such as metastasis, development, organization differentiation, cell proliferation, cell apoptosis, cell migration, invasion, and longevity." (PMID 28881636, 2017). "Further analysis suggested that modulation of angiogenesis-related genes (including ANGPTL4, FN1, HSPG2, SRPX2, KLK5, L1CAM, Prr22, FOXJ1, IL24, and TRIM54) potentially contributes to anlotinib resistance, as anlotinib is a multi-targeted anti-angiogenesis drug for cancer therapy." (PMID 31572680, 2019).
adenocarcinoma (1 paper, 2010). A common cancer characterized by the presence of malignant glandular cells. "Surprisingly, many of the cells that comprise the hyperplastic regions and eventual adenocarcinomas in the alveoli stain positively for the ciliated cell markers Foxj1 and acetylated tubulin." (PMID 20548776, 2010).
inflammation (1 paper, 2018). Aberrant reaction of the microcirculation characterized by movement of fluid and leukocytes from the blood into extravascular tissues. "We sought to determine if there were underlying associations between FOXJ1 localization score and the presence of eosinophilic or neutrophilic airway inflammation." (PMID 30459817, 2018). "Intriguingly, FOXJ1 localization score did not correlate with eosinophilic inflammation in NPs, which contrasted with the positive correlation between DNAH5 localization score and eosinophilic airway inflammation." (PMID 30459817, 2018).
FOXJ1 also shares sentences with these, for which no sentence is quoted: bladder cancer (3 papers); choroid plexus tumours (3); allergic rhinitis (2); communicating hydrocephalus (2); obstructive hydrocephalus (2); Ovarian Tumor (2); prostate carcinoma (2); Allergy (1); alopecia (1); Alzheimer disease (1); B-cell lymphoma (1); bacterial infections (1); Bamforth-Lazarus syndrome (1); Blepharophimosis (1); brain tumors (1); bronchiectasis (1); cardiovascular disease (1); chronic rhinitis (1); cystadenoma (1); cystic kidneys (1); endometrial tumours (1); Epicanthus inversus (1); hepatocellular carcinoma (1); intellectual disability with language impairment (1); invasive breast carcinoma (1); language disorder (1); mucinous ovarian carcinomas (1); Nail dystrophy (1); nasal polyps (1); normal pressure hydrocephalus (1).
A further 10 diseases each share a sentence with FOXJ1 in 1 paper.